IGF2BP2 (insulin like growth factor 2 mRNA binding protein 2)
Diseases named in the same sentence as IGF2BP2 in open-access papers (continued):
Sharing a sentence is not in itself a finding about the gene and the disease.
breast cancer (continued). "Overexpression of IGF2BP2 has been found to confer shorter survival and poor prognosis in multiple cancers, including breast cancer, hepatocellular carcinoma, and pancreatic ductal adenocarcinoma." (PMID 36569935, 2022). "From one cohort of 96 breast cancer patients, IGF2BP2 expression was significantly increased in patients with stages III and IV versus stages I and II." (PMID 34044876, 2021). "Compared to luminal or apocrine subtypes, IGF2BP2 is over-expressed in basal-like breast cancer tissues." (PMID 33568150, 2021). "IGF2BP2, as an oncofoetal protein, is located on chromosome 3q27 and is highly overexpressed in breast cancer cells and tissues." (PMID 34044876, 2021). "Ccn6/Wisp3 knockdown up-regulated the expression of IGF2BP2 in mice, who developed mammary carcinomas characterized by spindle and squamous differentiation, validated hallmarks of metaplastic breast carcinomas." (PMID 33568150, 2021). "Overexpression of IGF2BP2 has been reported in several types of solid cancer, such as breast cancer and esophageal adenocarcinoma." (PMID 32784624, 2020). "The autoimmune response to IGF2BP2 observed in hepatocellular carcinoma and colorectal, ovarian, and breast cancers supports the potential of autoantibodies against IGF2BP2 as biomarkers for cancer screening, diagnosis, and prognosis." (PMID 33246429, 2020). "Hepatitis B X-interacting protein (HBXIP) inhibits let-7 g expression to upregulate IGF2BP2, thus leading to the formation of a positive feedback loop of HBXIP/let-7 g/IGF2BP2/HBXIP to accelerate cell proliferation in breast cancer." (PMID 32767982, 2020). "As a result, IGF2BP2 and IGF2BP3 showed significant prognostic values of being risk factors (HR > 1) for OS of breast cancer patients." (PMID 33585234, 2020). "In concord with IGF2BP2 elevation in tumor tissue, autoantibody against IGF2BP2 is detected in 14.3% of blood samples from breast cancer patients, compared to only 5.6% in patients with benign tumors and 2.2% in healthy individuals." (PMID 29736175, 2018). "Autoimmune response to IGF2BP2 observed in hepatocellular carcinoma (HCC) and colorectal, ovarian, and breast cancer supports the potential of the autoantibody against IGF2BP2 as a biomarker in cancer screening, diagnosis, and prognosis." (PMID 29736175, 2018). "Future studies will validate whether LINC01133 recruits these (or other) E3 ligases to mediate IGF2BP2 ubiquitination in ER+ breast cancer." (PMID 40641925, 2025). "Furthermore, knockdown of IGF2BP2 also significantly decreased colony formation in a panel of breast cancer cell lines when compared with control shRNA-transduced cells." (PMID 40347943, 2025). "Our research elucidated that IGF2BP2 could partly recuse the suppressing effect of LINC01133 on ER+ breast cancer, which inferred that IGF2BP2 is also beneficial to the aggressive phenotype of the ER+ breast cancer." (PMID 40641925, 2025). "Thus, we first overexpressed and silenced IGF2BP2 in breast cancer cells, and si-IGF2BP2-#3 with the best inhibitory effect was selected for the follow-up experiments." (PMID 38782769, 2024). "In addition, knockdown or overexpression of IGF2BP2 or QKI reversed the effect of GAS5 on the proliferation of breast cancer cells, respectively." (PMID 38782769, 2024). "We elucidated that GAS5 suppressed breast cancer growth via IGF2BP2/QKI, and this inhibitory effect could be attenuated by FTO." (PMID 38782769, 2024). "We also found decreased IGF2BP2 expression in breast cancer tissues through UALCAN database." (PMID 38782769, 2024). "Finally, we investigated the biological functions of the FTO/GAS5/IGF2BP2/QKI axis in breast cancer." (PMID 38782769, 2024). "Next, we explored the biological functions of the FTO/GAS5/IGF2BP2/QKI axis in breast cancer." (PMID 38782769, 2024).
breast cancer (continued). "Additionally, in MDA-MB-231 and MCF-7 cells, miR-1193 suppresses the expression and activation of the ERK and PI3K/Akt signalling pathways by inhibiting IGF2BP2 translation and reducing the proliferation and invasion of human breast cancer cells." (PMID 34044876, 2021). "In patients with early-stage breast cancer, IGF2BP2 overexpression is also correlated with short survival, and therefore IGF2BP2 may be a useful serum biomarker for breast cancer screening and diagnosis." (PMID 34044876, 2021). "However, over-expression of miR-1193 inhibits proliferation and invasion of breast cancer cells by binding the 3′UTR region of IGF2BP2 mRNA, activating ERK and PI3K/Akt signaling pathways." (PMID 33568150, 2021). "Immunohistochemistry demonstrates frequent elevation of IGF2BP2 in breast cancer patients." (PMID 29736175, 2018). "Importantly, a high level of its mRNA correlates with a short survival, suggesting a potential prognostic value of IGF2BP2 in breast cancer." (PMID 29736175, 2018). "Indeed, overexpression of IGF2BP2 in basal-like breast cancer and esophageal adenocarcinoma predicts short survival of the patients." (PMID 29736175, 2018). "Our findings revealed the downregulation of LINC01133 in ER+ breast cancer and provided novel insight to the role of METTL3/YTHDF2/LINC01133/IGF2BP2 axis in ER+ breast cancer, which might offer a novel perspective in the design and development of novel anticancer drugs." (PMID 40641925, 2025). "IGF2BP2 is a carcinomatous fetal gene that is expressed at lower levels in normal adult tissues than in fetal liver tissues and is overexpressed in various types of cancer, such as glioblastoma, liver cancer, and breast cancer, thus making it a promising therapeutic target in cancer." (PMID 39281280, 2024). "Recently, an intriguing study reported that IGF2BP2 promoted the degradation of the RNA transcript encoding ATP6V1A, a catalytic subunit of the vacuolar ATPase, thus impairing lysosomal function and resulting in a unique secretome that greatly enhances breast cancer cell invasiveness." (PMID 38250159, 2024). "A comparison of expression levels across breast cancer subtypes revealed an upregulation of the readers IGF2BP1, IGF2BP2, and IGF2BP3 in basal cases, whereas other m6A readers manifested a more homogeneous expression across subtypes." (PMID 40918643, 2025). "For instance, in breast cancer stem-like cells, AURKA strengthens the binding of IGF2BP2 to stabilize m6A-modified DROSHA, resulting in the maintenance of breast cancer stemness." (PMID 38281999, 2024). "LncRNA GAS5 expression decreased in breast cancer and was regulated by FTO-mediated m6A modification in an IGF2BP2-dependent manner, resulting in decreased GAS5 stability and expression." (PMID 38782769, 2024). "In breast cancer, eight genes (METTL3, KIAA1429, ZC3H13, FTO, YTHDF1, YTHDF2, IGF2BP2, and IGF2BP3) were significantly enriched in tumor cells compared to immune or stromal cells." (PMID 35794212, 2022). "In breast cancer stem-like cells (BCSC), aurora kinase A (AURKA) binds to IGF2BP2 and strengthens IGF2BP2 to stabilize DROSHA mRNA in an m6A-modified way, thereby increasing BCSC stemness maintenance." (PMID 35541906, 2022). "In triple-negative breast cancer, IGF2BP3 and IGF2BP2 synergistically recruited CNOT1 complex, reduced the stability of progesterone receptor and ultimately promoted the migration and metastasis of breast cancer." (PMID 35676262, 2022). "With the increase of malignancy of breast cancer, the expression level of several m6A RNA methylation regulators, such as FTO, HNRNPA2B1 YTHDC1, IGF2BP1, IGF2BP2 and IGF2BP3, decreased or increased." (PMID 34141492, 2021). "In addition, suppressed IGF2BP2 could hinder cell proliferation and invasion in breast cancer." (PMID 33585234, 2020). "Other genes selected by Rlogreg, namely KISS1, IGF2BP2, CALCA, PLA1A, and FAM171A1, have been reported to be related to breast cancer or other types of cancer." (PMID 32795265, 2020).
breast cancer (continued). "As a biomarker predictive of response to the MEK inhibitor AZD6244 in breast cancer, we identified ENST00000346192, one of the longest isoforms of the insulin-like growth factor 2 mRNA-binding protein 2 (IGF2BP2), which codes a protein with 556 amino acids." (PMID 29066719, 2017). "In breast cancer (BRCA), the model selected HNRNPC, IGF2BP2, IGF2BP3, FTO, METTL16, and ALKBH1." (PMID 40565233, 2025). "Conversely, IGF2BP2 silencing could partially attenuate the promoting effects resulting from LINC01133 downregulation on proliferation, migration, and invasion of ER+ breast cancer cells, respectively." (PMID 40641925, 2025). "Furthermore, biological function experiments showed that GAS5 suppressed breast cancer growth via IGF2BP2/QKI, and this inhibitory effect was modulated by FTO both in vitro and in vivo, thus representing a promising strategy for the treatment of breast cancer." (PMID 38782769, 2024). "GAS5 recruited IGF2BP2 to target QKI and upregulated QKI expression in breast cancer cells." (PMID 38782769, 2024). "Significant elevation of IGF2BP2 expression in patients with head and neck squamous cell carcinoma (HNSC) was observed, whereas its expression was decreased in some other cancers, such as breast cancer and renal clear cell carcinoma." (PMID 38250159, 2024). "A recent study demonstrated that IGF2BP2 promoted the degradation of the RNA transcripts of the ATP6V1A gene, thereby impairing lysosomal function and resulting in a unique secretome that greatly enhances breast cancer cell invasiveness." (PMID 38250159, 2024). "For example, some tumors such as bile duct cancer (CHOL), head and neck cancer (HNSC), lung squamous cell carcinoma (LUSC), GBM, STAD, THCA, and BLCA exhibited high IGF2BP2 expression levels, while KIRC, breast cancer (BRCA), and UCEC were characterized by low levels of IGF2BP2 expression." (PMID 36686749, 2022). "IGF2BP1, IGF2BP2 and IGF2BP3, members of the IGF2BP family, modulate RNA splicing, translation, processing, and stability and thereby affect cell proliferation, differentiation, invasion and metastasis in breast cancer." (PMID 34044876, 2021). "Different from IGF2BP2 and IGF2BP3, although the oncogenic roles of YTHDC2 and RBM15 have been identified in colon cancer and acute megakaryoblastic leukemia, their functions in breast cancer await to be identified." (PMID 33585234, 2020). "In addition, detection of IGF2BP2 expression in breast cancer tissues and corresponding adjacent noncancerous normal tissues revealed the decrease of IGF2BP2 in breast cancer tissues." (PMID 38782769, 2024). "In conclusion, GAS5 represses the growth of breast cancer through regulating the IGF2BP2/QKI pathway, and this inhibitory effect is modulated by FTO-mediated m6A modification, suggesting that the FTO/GAS5/IGF2BP2/QKI pathway may be a potential target for breast cancer treatment." (PMID 38782769, 2024). "Consequently, the findings pertaining to the role of the piR-31115/METTL3/YAP1/IGF2BP2 signalling pathway in tumour angiogenesis may not be directly applicable to all TNBC cases or other breast cancer types." (PMID 39820521, 2025). "For example, in breast cancer, the oncogene Aurora kinase A (AURKA) enhances IGF2BP2’s binding to m6A-modified transcripts without promoting its nuclear translocation." (PMID 39596216, 2024).
diabetes (44 papers, 2010 to 2025). "Subsequent research revealed that IGF2BP2 variants diminish glucose-stimulated insulin secretion in the initial phase of diabetes progression, indicating an impact on pancreatic β-cell function." (PMID 39659616, 2024). "Although IGF2BP2 has been primarily studied in the context of diabetes and cancer, its association with inflammation and sepsis is not well-established." (PMID 38167131, 2024). "How Igf2bp2 impacts diet-induced obesity and diabetes risk, and its roles in mature white fat, have thus remained unclear." (PMID 35036870, 2022). "Dysregulation of IGF2BP2 is commonly associated with several human diseases such as cancer, diabetes or insulin resistance." (PMID 35876041, 2022). "Given that lncRAP2 is adipose-specific and conserved in mice and in humans, it represents an attractive target to selectively modulate Igf2bp2 activity within fat tissue to treat or prevent the progression of obesity-linked diabetes." (PMID 35036870, 2022). "We also found that Igf2bp2 trends lower in adipocytes of leptin-deficient (ob/ob) and leptin receptor-deficient (db/db) obese mice, which model diabetes onset and progression." (PMID 35036870, 2022). "A well-known example is SOD1 related to neuroinflammation, hyperthyroidism, hypertensive disease (associated also with GJA1), diabetes mellitus (associated also with IGF2BP2) and depressive disorders (associated also with S100B)." (PMID 34570756, 2021). "Even though IGF2BP2 SNPs are widely associated with the risk of developing diabetes, the relationship between expression patters of the resultant proteins and human metabolic diseases and cancers vary among ethnic populations." (PMID 33568150, 2021). "The risk of these variants was different among the three main Malaysian races Moreover, certain IGF2BP2 haplotypes and diplotypes strengthen the risk of diabetes." (PMID 23029108, 2012). "Interestingly, IGF2BP2 can preferentially regulate glucose and lipid metabolism, and thus IGF2BP2 is considered as diabetes associated gene that impairs insulin secretion." (PMID 35541906, 2022). "In addition, some studies have reported that the single nucleotide polymorphism (SNP) of IGF2BP2 is associated with diabetes and non-small-cell lung cancer (NSCLC)." (PMID 32784624, 2020). "The IGF2BP2 haplotypes and diplotypes increased the risk of diabetes in Malaysian subject." (PMID 23029108, 2012). "In these organs, small quantitative differences in Igf2bp2 expression subtly affects processes such as food uptake, metabolism, feeding behavior, or more complex behavioral features that affects physical activity and, ultimately, the lifetime risk of developing obesity and diabetes." (PMID 35002969, 2021). "Further study on functional differences between the two isoforms may provide insight into how cells regulate the expression and activity of these two isoforms and may shed light on how polymorphisms in Igf2bp2 sequences contribute to the risk of developing diabetes." (PMID 22427968, 2012). "However, rather little is known about the structure and function of the IGF2BP2 protein, and the manner in which its activity might influence diabetes risk." (PMID 22427968, 2012). "Collectively, these findings suggest a potential role for IGF2BP2 rs11705701 in diabetes development." (PMID 39659616, 2024). "Studies have demonstrated that several genes linked to T2DM risk are also related to GDM, and polymorphisms in HHEX, IGF2BP2, and FTO have been linked to decreased β-cell function and diabetes risk." (PMID 39659616, 2024). "For example, instruments are from genes TCF7L2, IGF2BP2, NOTCH2, CDKAL1, PABPC4, FTO and JAZF1, known to be associated with diabetes and that have been further significantly associated with the metabolites." (PMID 39349772, 2024). "IGF2BP2 has been identified as a promoter of diabetes mellitus and an oncogene that promotes several types of tumors; however, its role in hDPSC proliferation and differentiation remains elusive." (PMID 38443392, 2024).
diabetes (continued). "Recent publications have focused mainly on the role of IGF2BP2 and IGFBP3 variants in diabetes and cancer risk." (PMID 38468402, 2024). "Intriguingly, Igf2bp2-null mice are resistant to diet-induced obesity and diabetes, though this is likely due to underdeveloped white and overactive brown fat —a tissue that is much less prevalent in adult humans." (PMID 35036870, 2022). "We further find that the levels of lncRAP2 and Igf2bp2 in adipocytes are reduced during the development of obesity and diabetes." (PMID 35036870, 2022). "Murine models have uncovered the role of IGF2BP2 in metabolic diseases including diabetes, obesity, fatty liver and among others." (PMID 33568150, 2021). "Previous GWASs have shown that genetic variation of ETV5 is predictive of BMI in multiple populations including the Europeans while IGF2BP2 predictive of the onset of diabetes in European populations and a Chinese Han population." (PMID 32366963, 2020). "Disruption of IGF2BP2 function, unsurprisingly, results in a variety of diseases and disorders such as diabetes and cancer." (PMID 29736175, 2018). "The IGF2BP2 variant rs7651090 is described in Malaysian subjects with glutamic acid decarboxylase antibody (GADA)-negative diabetes." (PMID 38674416, 2024). "Targeting the regulatory mechanism of IGF2BP2 may promote the development of new therapeutic strategies for diabetes, fatty liver, and pancreatic, liver, breast, and oral cancers." (PMID 38443392, 2024). "For example, IGF2BP2 may influence glucose homeostasis and the progression of diabetes by modulating laminin-β2 mRNA levels, but whether this regulation occurs through recognizing m6A modifications requires further verification." (PMID 39342406, 2024). "IGF2BP2 is highly expressed in pancreatic islets, but its contribution to diabetes is unclear." (PMID 35163144, 2022). "Additionally, IGF2BP2 regulates multiple physiological processes including embryonic development, neuronal differentiation and metabolism, insulin resistance in diabetics and carcinogenesis." (PMID 33568150, 2021). "IGF2BP2 rs4402960 and rs1470579 are the most common SNPs in diabetes." (PMID 33568150, 2021). "Accordingly, we summarize how IGF2BP2 SNPs participate in the development of diabetes." (PMID 33568150, 2021). "Indeed IGF2BP2 modulates cellular metabolism in human metabolic diseases such as diabetes, obesity and fatty liver through post-transcriptional regulation of numerous genes in multiple cell types." (PMID 33568150, 2021). "Later on, the IGF2BP2 variant was found to decrease glucose-stimulated insulin secretion in the first but not the second phase of diabetes development." (PMID 33568150, 2021). "Other interesting GDAs involved the IGF2BP2 genes and diabetes mellitus, and GALC and seizures." (PMID 34570756, 2021). "This research indicates IGF2BP2 might serve as a new invention target for dealing with impaired wound healing in clinic, such as diabetes, vascular disease, and aging." (PMID 34753397, 2021). "In region chr3:185324933-186022133, there may exist two independent causal SNPs: rs9816226 (nearest gene: ETV5) for BMI and rs1470580 (in IGF2BP2) for diabetes." (PMID 32366963, 2020). "In conclusion, IGF2BP2 alternative variants were associated with GADA negative diabetes in Malaysian subjects." (PMID 23029108, 2012). "The additive genetic model adjusted for age, race, gender and BMI showed that alternative variants; rs6777038, rs16860234 and rs7651090 of IGF2BP2 associated with GADA negative diabetes (OR = 1.21; 1.36; 1.35, P = 0.03; 0.0004; 0.0002, respectively)." (PMID 23029108, 2012). "Association of IGF2BP2 polymorphism with GADA negative diabetes among Malaysian subjects and ethnic groups." (PMID 23029108, 2012). "rs4402960 of IGF2BP2 was associated with GDM (OR = 1.21, 95% CI = 1.08–1.36, P = 0.001) in four studies (n = 8,732), also in the subgroup among East Asian diabetes mellitus patients (OR = 1.24, 95% CI = 1.07–1.44, P = 0.004)." (PMID 23029294, 2012).